RNU6-1245P (RNA, U6 small nuclear 1245, pseudogene)
Gene: Small nuclear RNA gene on chromosome 1 (27,824,538 to 27,824,643, forward strand). Ensembl gene ENSG00000223062.
Homologues: Orthologues: chimpanzee U6 (99% identical), macaque U6 (83% identical), dog U6 (75% identical). Paralogues in human: RNU6-1084P (85% identical), RNU6-1214P (81% identical), RNU6-333P (81% identical), RNU6-38P (81% identical), RNU6-1145P (80% identical), RNU6-1158P (80% identical), RNU6-1316P (80% identical), RNU6-207P (80% identical), RNU6-20P (80% identical), RNU6-21P (80% identical), RNU6-310P (80% identical), RNU6-574P (80% identical), and 1286 more.